TEX38 (testis expressed 38)
Description:
Plays an essential role in male fertility. TEX38 and ZDHHC19 form a complex in developing sperm. This complex may regulate S-palmitoylation of the proteins that are essential for generating functional sperm with the correct morphology.
Synonyms: ATPAF1-AS1; C1orf223; LOC374973; THEG4
Tractability: Antibody: UniProt predicts a signal peptide or a membrane-spanning region; its Gene Ontology location is reachable by antibodies, with medium confidence.
Gene: Protein-coding gene on chromosome 1 (46,668,855 to 46,673,594, forward strand). Ensembl gene ENSG00000186118.
Subcellular location: Cell membrane
Subcellular location (Human Protein Atlas): Vesicles
Gene Ontology:
Cellular component: plasma membrane
Genetic constraint (gnomAD): Loss-of-function variants: 6 observed, 4.79 expected, observed/expected ratio (o/e) 1.25, 90% interval 0.66 to 1.89. That is too few expected variants to judge how well the gene tolerates losing a copy. Missense variants: 218 observed, 257.56 expected, observed/expected ratio (o/e) 0.85, 90% interval 0.76 to 0.95. Synonymous variants: 110 observed, 108.03 expected, observed/expected ratio (o/e) 1.02, 90% interval 0.87 to 1.19.
Homologues: Orthologues: chimpanzee TEX38 (95% identical), macaque TEX38 (94% identical), dog TEX38 (76% identical), rabbit TEX38 (74% identical), rat Tex38 (70% identical), pig TEX38 (69% identical), mouse Tex38 (66% identical), guinea pig TEX38 (64% identical).
Diseases named in the same sentence as TEX38 in open-access papers:
TEX38 is named in the same sentence as 1 disease in open-access papers, as found by Europe PMC text mining. Sharing a sentence is not in itself a finding about the gene and the disease.
TEX38 shares sentences with these, for which no sentence is quoted: male infertility (1 paper).